ITGA3 (integrin subunit alpha 3)
Diseases named in the same sentence as ITGA3 in open-access papers (continued):
Sharing a sentence is not in itself a finding about the gene and the disease.
osteoarthritis (2 papers, 2024 to 2025). A noninflammatory degenerative joint disease occurring chiefly in older persons, characterized by degeneration of the articular cartilage, hypertrophy of bone at the margins and changes in the synovial membrane. "High levels of ITGA3 have been positively associated with osteoarthritis." (PMID 41226336, 2025). "Itga3 expression has been found to be downregulated in PBMCs from OA (osteoarthritis) patients, and a previous study has reported that the absence of Prg4 from the synovium leads to OA and aberrant fibroblast expansion and proliferation." (PMID 39235454, 2024).
osteosarcoma (2 papers, 2021 to 2022). A usually aggressive malignant bone-forming mesenchymal neoplasm, predominantly affecting adolescents and young adults. "ITGA3 polymorphisms might influence the osteosarcoma in terms of the incidence rate, metastatic status and prognosis, which was considered as a potential signature for osteosarcoma." (PMID 34335109, 2021).
skin tumor (2 papers, 2014 to 2020). "Loss of ITGA3 prevents skin tumor formation by promoting epidermal turnover and depletion of slow-cycling cells." (PMID 25254241, 2014). "In this study, we showed that the contribution of HB SCs to skin tumors is minimal, and even further reduced in the K19 Itga3 KO mice." (PMID 32423907, 2020).
adrenocortical tumor (1 paper, 2014). "Moreover, ITGA3 mRNA expression was inversely correlated with ZNF367 mRNA expression in human adrenocortical tumor samples (r = - 0.37, p = 0.015)." (PMID 25047265, 2014).
Aortic dissection (1 paper, 2021). Aortic dissection refers to a tear in the intimal layer of the aorta causing a separation between the intima and the medial layers of the aorta. "In addition, ITGA3 and ITGA5 were identified as new biomarkers for the onset of acute aortic dissection." (PMID 33953793, 2021).
Arthritis (1 paper, 2024). Inflammation of a joint. "Interestingly, during Mir221/222 overexpression in arthritis, the expression of ECM-related molecules in SFs was found altered and, more specifically, Prg4 and the integrin component Itga3 were downregulated." (PMID 39235454, 2024).
B cell lymphomas (1 paper, 2025). "Therefore, we studied the association of CD151 with ITGA3 in normal healthy B cells and B cell lymphomas." (PMID 40464949, 2025).
cervical squamous cell carcinoma (1 paper, 2024). A squamous cell carcinoma arising from the cervical epithelium. "MUC1 regulates ERK phosphorylation, and subsequently upregulates ITGA2 and ITGA3 expression to promote tumorigenesis in cervical squamous cell carcinoma." (PMID 38702644, 2024). "Collectively, these data demonstrated that the ITGA family of ITGA2 and ITGA3 are novel oncogenes in CSCC and may be new therapeutic targets for cervical squamous cell carcinoma." (PMID 38702644, 2024).
chordoma (1 paper, 2023). Chordomas are rare malignant tumors arising from embryonic remnants of the notochord in axial skeleton. "Interestingly, in recurrent chordomas, interactions involving FN1 and ITGAV/ITGB1, as well as FN1 and ITGA3/ITGB1, emerged as significant contributors to this communication network." (PMID 37784253, 2023).
colonic dysplasia (1 paper, 2025). "Although this limitation precluded use of the KPC:APC mouse model to assess tumorigenesis and progression, we were able to show that the genetic deletion of Itga3 in the colon did not alter extensive inflammation and the colonic dysplasia that forms in these mice." (PMID 39941740, 2025).
colorectal tumours (1 paper, 2015). "Multivariate mathematical models demonstrated an association between hyperexpression of the ITGAV and ITGA6 integrins and GS, and also between the ITGA3 integrin and DFS, in patients with colorectal tumours." (PMID 26674523, 2015). "In conclusion, a multivariate mathematical model was generated that demonstrated an association between hyperexpression of the integrins, ITGAV and ITGA6, and GS, and also between the ITGA3 integrin and DFS, in patients with colorectal tumours." (PMID 26674523, 2015).
cystic tumors (1 paper, 2019). "(b) Quantification of solid vs cystic tumors Itga3 KO and WT mice determined by pathological analysis of excised tumors." (PMID 31101121, 2019). "No positive staining was observed in any of the analyzed solid tumors, and a comparable amount of apoptosis was detected in cystic tumors of Itga3 KO and WT mice." (PMID 31101121, 2019).
emphysema (1 paper, 2023). "KEGG pathway analysis showed upregulation of the term “ECM-receptor interaction”, which includes integrin subunit alpha 3 (ITGA3), collagen type VI α1 chain (COL6A1), and heparan sulfate proteoglycan 2 (HSPG2) in the non-emphysema subgroup." (PMID 38203236, 2023).
Fanconi anemia (1 paper, 2023). Fanconi anemia (FA) is a hereditary DNA repair disorder characterized by progressive pancytopenia with bone marrow failure, variable congenital malformations and predisposition to develop hematological or solid tumors. "Among these 14 pathways, four major pathways were enriched: SNARE interactions involved in the vesicular transport (BET1 and STX6), leishmaniasis (FCGR1A, CYBB, and FOS), hematopoietic cell lineages (FCGR1A, ITGA3, MME, and CD5) and Fanconi anemia pathway (SLX4, ATR, and TELO2)." (PMID 37601105, 2023).
Hyperglycemia (1 paper, 2025). An increased concentration of glucose in the blood. "Hyperglycemia also upregulates FLOT2 and downregulates ITGA3 via ROS and TGF-β1-dependent epigenetic remodeling of their gene promoters, reducing integrin-mediated podocyte adhesion and actin stability." (PMID 41368354, 2025).
hypertrophic cardiomyopathy (1 paper, 2013). A condition in which the myocardium is hypertrophied without an obvious cause. "The present results showed that many genes significantly altered in cell development and hypertrophic cardiomyopathy by overexpressed atrogin-1, Myh6, Serca2 (ATP2A2) and Prkcz were significantly up-regulated, whereas Itga3 (also known as CD49c) and Foxa2 were down-regulated.." (PMID 23335977, 2013).
Intellectual disability (1 paper, 2020). "Published reports of intellectual disability in patients with deletion of COL1A1 and adjacent genes, including ITGA3, elevate our concern, but to date, the proband's (and sibling's) intellectual and behavioral development have been within normal limits." (PMID 32281310, 2020).
keratoacanthoma (1 paper, 2020). A dome-shaped, rapidly growing skin lesion composed of well differentiated squamous cells. "By the end of the treatment (P196), ulcerating tumors were observed in one K19 Itga3 KO and three WT mice, which were identified as SCCs (K19 Itga3 KO and WT) and keratoacanthomas with carcinomatous changes (K19 Itga3 WT) by histological analysis." (PMID 32423907, 2020). "Furthermore, K19 Itga3 KO mice developed also high malignancy–grade tumors such as spindle cell sarcoma and mixed basal SCC in addition to the SCCs and keratoacanthomas with carcinomatous changes." (PMID 32423907, 2020).
metastasis (1 paper, 2021). The spread or migration of cancer cells from one part of the body (where they first appeared) to another. "Therefore, we speculated that high expression of ITGA3 gene could be used as a predictor for lymph node metastasis and recurrence of PTC." (PMID 35174063, 2021).
metastatic cancer (1 paper, 2013). A carcinoma which has spread from the original site of growth to another anatomic site. "K-M curves for LNM showed that a [high-ITGA3/CD9 and YK4] status can identify highly metastatic cancer capable of early lymph node invasion." (PMID 24006899, 2013).
papilloma (1 paper, 2020). A benign epithelial neoplasm that projects above the surrounding epithelial surface and consists of villous or arborescent outgrowths of fibrovascular stroma. "To determine whether papillomas can arise from Cre-initiated HB keratinocytes in K19 Itga3 KO and WT mice, we have analyzed the cross-sectional areas of 321 and 365 tumors, respectively, for the presence of GFP." (PMID 32423907, 2020). "Remarkably, most tumors were negative for GFP, and only one small papilloma isolated from K19 Itga3 WT mouse consisted almost entirely of GFP-positive cells." (PMID 32423907, 2020). "In papillomas, CCN2 expression could be observed in isolated epithelial or stromal cells and occasionally in cell clusters, which did not correlate to the HB-originating GFP-positive areas in consecutive sections of tumors, isolated from K19 Itga3 WT mice." (PMID 32423907, 2020). "To this end, we performed RNA sequencing of GFP-positive keratinocytes isolated from the skin of K19 Itga3 KO and WT mice during the initiation stage of tumorigenesis induced by short-term DMBA/TPA treatment, which has been shown to be sufficient for the outgrowth of papillomas." (PMID 32423907, 2020).
phaeochromocytoma (1 paper, 2016). "All of the genes, but 2 (ITGA3 and GRB10), associated with the Wnt signaling pathway were upregulated in ZG versus ZF samples, irrespective of whether the comparison was made separately for ZG adjacent to an APA or a phaeochromocytoma." (PMID 27777363, 2016).
pulmonary fibrosis (1 paper, 2025). Chronic progressive interstitial lung disorder characterized by the replacement of the lung tissue by connective tissue, leading to progressive dyspnea, respiratory failure, or right heart failure. "Using an adeno‐associated virus 6 targeting the lung epithelium to ITGA3 knockdown, we found that ITGA3 deficiency eliminated the improvement of NPNT on cell aging and pulmonary fibrosis." (PMID 40444575, 2025). "This study further investigated whether the protective role of NPNT in pulmonary fibrosis is dependent on ITGA3." (PMID 40444575, 2025). "Therefore, we hypothesized that NPNT might act on ITGA3 to regulate the intracellular Hippo/YAP1 axis, influence the aging of alveolar epithelial cells, and subsequently impact the progression of pulmonary fibrosis." (PMID 40444575, 2025).
thyroid (1 paper, 2021). "Recently the role of ITGA3 in thyroid carcinogenesis has been investigated." (PMID 34208249, 2021).
tuberculosis (1 paper, 2024). A chronic, recurrent infection caused by the bacterium Mycobacterium tuberculosis. "The THBS signaling pathway is widely present in the region enriched with macrophages in the tuberculosis spot, indicating that macrophages and fibroblasts interact depending on THBS1/2-CD36/SDC4/ITGA3/ITGB1, which may be a key pathway for tuberculosis progression." (PMID 39431015, 2024).
villous adenocarcinoma (1 paper, 2014). An adenocarcinoma characterized by the presence of a villous architectural pattern. "The overexpression of the matrix extracellular genes ITGA-3 and ITGB-5 is associated with advanced stage tumors, and the genes MMP-2 and MMP-9 are overexpressed in mucinous and villous adenocarcinoma type tumors, respectively." (PMID 24737953, 2014).
tumor (102 papers, 2012 to 2026). "ITGA3 is closely associated with a poor prognosis in various cancers, and its expression is upregulated in most tumor tissues." (PMID 40649881, 2025). "Other studies present NOX4 and ITGA3 as relapse risk markers with important clinical interest, in order to understand how the mechanism of tumor’s progression to metastasis is activated." (PMID 34073426, 2021). "High risk of tumor recurrence, according to the 2015 American Thyroid Association guidelines, was associated with higher ITGA3 expression, whereas higher expression of ITGA2 and ITGAV correlated with intermediate-risk." (PMID 34208249, 2021). "The NP-TRFIA assay was evaluated for its efficacy in the identification of known tumor-associated proteins (EpCAM and ITGA3) on the surface of EVs." (PMID 31296879, 2019). "Both false positive cases had a tumor size of over 35 mm, suggesting a higher diagnostic reliability for [high-ITGA3/CD9 and high-ITGB4/JUP] status in early OSCC." (PMID 24006899, 2013). "Primary site recurrence (PSR) was significantly associated with high-ITGA3/CD9, tumor size, T3-4 and positive margin, while distant metastasis was associated with high-ITGA3/CD9, a high ITGB4/JUP ratio (high-ITGB4/JUP), and YK4." (PMID 24006899, 2013). "Studies indicate that ITGA3 expression levels in BC may be linked to tumor development and malignancy." (PMID 40181838, 2025). "Nagata's research suggested that ITGA3 could act as a tumor‐promoting gene in HNSCC and be associated with an unfavorable prognosis." (PMID 34331382, 2021). "Further in-depth analysis of the roles of ITGA3/5/6 in HNSC reveals that ITGA3/5/6 is closely related to multiple pathways in tumor development." (PMID 41602372, 2026). "Further analysis of the expression relationship between tumor tissues and adjacent paired tissues of ITGA3, ITGA5, and ITGA6 in HNSC reveals that the expressions of ITGA3, ITGA5, and ITGA6 are significantly increased in tumor tissues." (PMID 41602372, 2026). "To validate the observed accumulation of integrins on the tumor cell surface, we focused on the most enriched integrins upon AP2 loss, namely ITGB1, ITGB6, ITGA2, and ITGA3." (PMID 40050266, 2025). "In ROC analysis, especially ITGA3–WFL demonstrated remarkable performance in discriminating between tumor and normal tissues." (PMID 40287842, 2025). "Integrin subunit member 3 (ITGA3), which acts as an adhesion molecule and is also involved in tumor biology, as well as the extracellular matrix protein 1 (ECM1), is associated with endochondral bone formation and angiogenesis." (PMID 40013338, 2025). "This duality emphasizes the bi-directional role of ITGA3 in BC and underscores the necessity for more investigation to define various impact mechanisms by which ITGA3 controls tumor behavior." (PMID 40181838, 2025). "Remarkable differences between normal and tumor tissues in GalNAc‐specific WFL assays were observed in ITGA3 and ITGB1." (PMID 40287842, 2025). "ITGA3, an integrin family member, plays an essential role in tumor cell adhesion, migration, and invasion." (PMID 40181838, 2025). "In mice models, deletion of homotrimeric collagen I or suppression of ITGA3 in tumor cells improved overall survival and tumor T-cell infiltration." (PMID 38659022, 2024). "In GSE146409, we found that ITGA3 was highly expressed in tumor cells, which was the same as our previous results of TCGA-LIHC differential analysis." (PMID 39085893, 2024). "As a result, ITGA3 is recognized as a potential therapeutic target in cancer treatment, warranting further investigation into its role in tumor biology and therapeutic interventions." (PMID 39697342, 2024). "ITGA3, belonging to the integrin family, has been reported to interact with extracellular matrix proteins and promote tumor cell proliferation, migration and survival." (PMID 39218967, 2024).
tumor (continued). "Clinicopathological characterization indicated that PKM2 or ITGA3 overexpression was associated with age, serum AFP, TNM stage, BCLC stage, tumor number, tumor size, and microvascular invasion." (PMID 39070142, 2024). "ITGA3 downregulation hindered tumor cell invasion and proliferation by regulating the FAK/PI3K/AKT pathway and epithelial-mesenchymal transition." (PMID 39749345, 2024). "Although ITGA3 is widely expressed in normal organisms, under the influence of tumor gene induction, changes in chromatin structure along with high expression of growth factors and their receptors disrupt its expression pattern leading to tumorigenesis." (PMID 39070142, 2024). "Lastly, wound healing and transwell assays were conducted to elucidate the role of ITGA3 in tumor metastasis." (PMID 39085893, 2024). "As ITGA3 is a crucial protein regulating tumor EMT (epithelial-mesenchymal transition), we further confirmed that overexpression of CCDC25 suppresses EMT in ccRCC cells." (PMID 38570766, 2024). "ITGA3, a member of the integrin family, is frequently characterized as an oncogenic factor across various tumor types." (PMID 39697342, 2024). "Mice injected with ITGA3-KO YUMMER1.7 cells showed a significant increase in tumor growth compared with mice injected with the NTC, indicating that loss of ITGA3 confers increased tumorigenesis." (PMID 38319712, 2024). "To investigate whether the pEMT biological process is potentially caused by SDC1, SDC4, ITGA2, and ITGA3 expressed by CAFs, we further focused on the correlation between the ligand genes from CAFs as well as from Angiogenic_EC with the abundance of malignant tumor cells undergoing pEMT." (PMID 38002057, 2023). "We found that the key genes, especially SDC1, SDC4, ITGA2, and ITGA3, in malignant cells that interacted with CAFs and Angiogenic_EC were positively correlated with the pEMT score in tumor cells." (PMID 38002057, 2023). "The results of the Mann–Whitney U test of eight microarray datasets showed that PAAD tumor tissues had higher ITGA3 levels than control tissues (p < 0.05)." (PMID 36561844, 2022). "Tumor samples with more than 4 mm thickness exhibited significantly lower relative expression levels of ITGA3, ITGA6, ITGA9, ITGAV, and ITGB1 than samples belonging to the 2–4 mm Breslow thickness category (Mann–Whitney test, p < 0.05)." (PMID 36091936, 2022). "In summary, this study showed that ITGA3 expression was greater in PCa tumor tissues than in adjacent non-tumor tissues." (PMID 36561844, 2022). "Our present study showed that the expression level of ITGA3 in PCa tumor tissues was greater than that in the adjacent non-tumor tissues." (PMID 36561844, 2022). "The expression of ITGA3 was significantly negatively correlated with tumor purity and B cell infiltration and positively correlated with macrophage infiltration." (PMID 34094951, 2021). "Silencing ITGA3 inhibited tumor cell migration and invasion through regulating FAK/PI3K/AKT and FAK/Src signaling mechanisms." (PMID 33925460, 2021). "Studies have shown that ITGA3 is highly expressed in multiple cancers and is related to tumor progression and poor prognosis." (PMID 35174063, 2021). "In conclusion, ITGA3 coexpressed genes were mainly involved in tumor formation, regulating cell adhesion, migration, proliferation, apoptosis, and immune response." (PMID 34094951, 2021). "miRNA-144-5p inhibited ITGA3 expression in TC, and its overexpression remarkably reversed the tumor-promoting effects of overexpressed ITGA3 on the biological functions of TC." (PMID 34938358, 2021). "Disease-free survival analysis showed that tumors with higher expression of ITGA2 or ITGA3 had a shorter time between tumor recurrences." (PMID 34208249, 2021). "Combined with clinical information, the expression of ITGA3 was markedly different in patients with different T stages and N stages of the tumor." (PMID 34938358, 2021).